IL17F (interleukin 17F)
Diseases named in the same sentence as IL17F in open-access papers (continued):
Sharing a sentence is not in itself a finding about the gene and the disease.
COVID-19 (continued). "The results also suggest that either targeting IL-17F or abrogating the activity of both cytokines, targeting their common downstream receptor IL-17RC, could be another therapeutic avenue to attenuate the severe outcomes of COVID-19." (PMID 39493750, 2024). "Our results show an association between IL-17F and COVID-19 severity in the large BQC19 cohort rather than IL-17A, which may provide an explanation for the lack of efficacy when targeting IL-17A alone." (PMID 39493750, 2024). "The findings indicate that the IL-17F H161R variant does not influence the risk of COVID-19." (PMID 36349054, 2022). "In this study, we have investigated the impact of IL-17F activation on endothelial cells and its impact on neutrophil recruitment and ICAM-1 expression at the surface level in the context of acute COVID-19." (PMID 39493750, 2024). "Moreover, the association between IL17A/IL17F gene and COVID-19 severity was identified in a regression analysis that include age, sex, and underlying diseases as covariates, suggesting that IL17A/IL17F gene is involved in COVID-19 severity regardless of age, sex and underlying diseases." (PMID 35264675, 2022). "Antigen-specific production of cytokines related to a Th17 response was also consistently detected; PBMC from COVID-19 ARDS patients produced significantly more IL-17A, IL-17F and IL-22 than HC." (PMID 32591408, 2020). "Although Il-17A and IL-17F are known to signal through the same receptor IL-17RA/RC, the results obtained here from the analysis indicate that IL-17F and not IL-17A was significantly enriched in the plasma of patients with severe COVID-19." (PMID 39493750, 2024). "Among patients enrolled within 7 days of symptom onset, evidence of pro-inflammatory monocyte/macrophage (IL-1Ra, IL-1β, IL-6, CXCL10), NK cell (IL-15), Th1/Th17-pathway (IL-7, IL-15, IL-17F), and endothelial (VEGF-A) activation were apparent in patients with severe COVID-19." (PMID 38368384, 2024). "IL-17F, but not IL-17A, was significantly elevated in people with COVID-19 compared to healthy controls and with more severe disease." (PMID 39493750, 2024). "Conversely, during the acute phase of SARS-CoV-2 infection, CD4+ T cells from the lungs of patients with COVID-19 did not increase Th17-associated genes, including RORC, IL17A, and IL17F, and CCR6 expression was significantly reduced in patients with severe COVID-19." (PMID 36146622, 2022). "Because all the studied samples were collected from Japanese COVID-19 patients at discharge, it was not possible to determine whether IL17F could be used as a severity marker." (PMID 35264675, 2022). "We investigated the circulating levels of IFNγ, IL-4, sIL-4R, IL-5, IL-9, IL-17A, IL-17F, IL17-E/25, IL-22 and sCD30 in surviving and non-surviving severe COVID-19 patients and healthy controls." (PMID 36142255, 2022). "For instance, one patient with CSS had 1,080,000 pg/ml IL17f, whereas the average value among all patients with non-CSS COVID-19 is 1435 pg/ml." (PMID 33187979, 2020).
periodontitis (21 papers, 2014 to 2026). An acute or chronic inflammatory process that affects the tissues that surround and support the teeth. "In this regard, some gene variants of the IL‐23/IL‐17 axis and its receptors have been analyzed in periodontitis, but only associations with IL‐17A and IL‐17F have been found." (PMID 41536464, 2026). "Regarding the IL‐17F gene, nine studies evaluated the missense variant rs 763780 in 1184 individuals with periodontitis." (PMID 39887950, 2025). "The critical role of IL-17 in mediating bone loss was confirmed using a ligature model of periodontitis where local administration of mAbs to IL-17A or IL-17F inhibited bone destruction." (PMID 28497028, 2017). "A case-control study was conducted on patients with chronic periodontitis (CP) and healthy controls with the aim of evaluating possible association between interleukin 17A (IL17A) G197A (rs2275913) and IL17F T7488C (rs763780) polymorphisms and periodontitis." (PMID 26339129, 2015). "Moreover, further analysis demonstrated a high correlation between IL-17A+IL-17F- Th17 cells and attachment loss or probing depth suggesting that these IL-17 producing cells are involved in the pathogenesis of periodontitis." (PMID 39253090, 2024). "In this study, experimental periodontitis was associated with the progressive and increased presence of Th17 and Treg-related mediators in the gingiva (IL-6, IL-17A, IL-17F, RANKL, IL-10, TGF-β and GITR; P < 0.05), and the proliferation of both Treg and Th17 cells in cervical lymph nodes." (PMID 33149125, 2020). "This study analyzed six genetic variations of IL‐17A, IL‐17F, IL‐17R, and IL‐23R genes in people with periodontitis and peri‐implantitis." (PMID 39887950, 2025). "In patients with periodontitis, flow cytometry analyses of blood samples revealed an expansion of IL-17A+IL-17F- and IL-17A-IL-17F+ Th17 cells as compared to healthy controls." (PMID 39253090, 2024). "Among these cytokines IL-17A and IL-17F have been proposed to play a pivotal role in inflammatory disorders such as chronic periodontitis." (PMID 39253090, 2024). "In the paper that compared cytokine levels for 54 periodontitis patients and 40 healthy controls, cytokines IL‐1β, IL‐4, IL‐6, IL‐10, IL‐17A, IL‐17F, IL‐21, IL‐22, IL‐23, IL‐25, IL‐31, IL‐33, IFN‐γ, sCD40L and TNF‐α were measured in saliva and serum at baseline, 3, 6 and 12 months after treatment." (PMID 41580300, 2026). "This study analyzed a total of twenty‐eight genetic variants corresponding to the IL‐17A: rs 2275913 (68.4%), rs 3819024 (5.3%), rs 10484879 (5.3%); IL‐17F: rs 763780 (47.4%), IL‐17R: rs 879576 (11%) and IL‐23R: rs 11209026 (11%) genes in subjects with periodontitis and peri‐implantitis." (PMID 39887950, 2025). "Interestingly, exFoxp3TH17 cells in periodontitis-induced mice had much higher expression levels of effecter molecules such as Rorc, Il17a, Il17f, and Tnfsf11 than conventional TH17 cells." (PMID 29453398, 2018). "IL-6 induced by IL-17F or IL-17A may play a potential feedback loop in the pathogenesis of chronic periodontitis." (PMID 29670909, 2018). "However, to the extent of our knowledge, there are still less reports focused on the correlation between (IL-17A+ and/or IL-17F+) Th17 cells and periodontitis." (PMID 25525302, 2014). "Taken together, this clinical study indicated that IL-17A+ and/or IL-17F+ positive Th17 may participate in the periodontitis pathogenesis." (PMID 25525302, 2014). "Therefore, the present clinical study was designed to detect the expression levels of (IL-17A+ and/or IL-17F+) Th17 cells in periodontitis patients." (PMID 25525302, 2014). "Regarding intestinal tissue analyses, higher levels of IL-1β, IL-4, IL-6, IL-17A, IL17F, IL-21, IL-31, IL-33 and sCD40L were found in patients with IBD and periodontitis." (PMID 34501547, 2021). "High levels of IL-17A, IL-17F IL-22, IL-25, IL-33, IL-10 and INF-y were found in gingival biopsies compared with intestinal biopsies from patients with IBD and periodontitis." (PMID 34501547, 2021).
periodontitis (continued). "Regarding intestinal tissue analyses, higher levels of IL-1β, IL-4, IL-6, IL-17A, IL17F, IL-21, IL-31, IL-33 and soluble CD40 ligand (sCD40L) were found in patients having IBD activity and periodontitis." (PMID 34501547, 2021). "High miR-144-5p expression in chronic periodontitis was negatively correlated with COX2 and IL17F expression, suggesting that miR-144-5p could play a role in chronic inflammation." (PMID 31841443, 2019).
psoriatic arthritis (18 papers, 2014 to 2026). Joint inflammation associated with psoriasis. "For that purpose, we conducted a comprehensive literature search on PubMed for studies published between 2007 and 2025, using keywords such as “bimekizumab”, “IL-17”, “IL-17A”, “IL-17F”, “psoriatic arthritis”, and “ankylosing spondylitis”." (PMID 40076933, 2025). "In the double-blind, placebo-controlled phase 2 ARGO trial, patients with active psoriatic arthritis treated with a nanobody targeting IL-17A and IL-17F showed substantially better disease response rates compared with those receiving placebo treatment." (PMID 41053449, 2025). "The difference in the results for IL-17A and IL-17F can be used as a basis for distinguishing JIA from psoriatic arthritis, in which both blood cytokine levels are elevated." (PMID 38255240, 2024). "Below, we will review the role of the IL-23/IL-17 axis in the pathology of AxSpA including ankylosing spondylitis and psoriatic arthritis with a particular focus on IL-17A and IL-17F." (PMID 35861937, 2022). "A clinical trial revealed that IL-17F promotes an inflammatory response in patients with psoriatic arthritis." (PMID 32391010, 2020). "Furthermore, IL-17A, IL-17F, and their receptors are found in the inflamed synovium of patients with rheumatoid arthritis and psoriatic arthritis." (PMID 35861937, 2022). "Bimekizumab, a humanized monoclonal IgG1 antibody that neutralizes both IL-17A and IL-17F, has shown substantial efficacy in the treatment of psoriasis (PSO), psoriatic arthritis (PsA), and AxSpA." (PMID 40076933, 2025). "Bimekizumab can effectively and selectively inhibit IL-17A and IL-17F, being currently in the phase III clinical trial stage for the treatment of various inflammatory diseases, including plaque psoriasis, psoriatic arthritis." (PMID 37304306, 2023).
skin inflammation (17 papers, 2016 to 2025). "In the present study, to assess the effectiveness of targeting IL-17A and IL-17F in treating systemic amyloidosis and arteriosclerosis, KCASP1Tg mice were cross-mated with IL-17A-, IL-17F-, and IL-17AF-deficient mice, and observed until late stage of dermatitis." (PMID 39519167, 2024). "During skin inflammation, S. aureus epicutaneous exposure resulted in eosinophil infiltration where these cells had a comparable contribution to the skin inflammation as T cells, in an eosinophil-derived IL-17A and IL-17F dependent manner." (PMID 40005560, 2025). "These compounds aim to suppress Th17 differentiation and inhibit the production of pro-inflammatory cytokines like IL-17A and IL-17F, which are significant contributors to skin inflammation and keratinocyte hyperproliferation in conditions like psoriasis." (PMID 41301460, 2025). "A study using a long-lasting dermatitis mouse model that overexpressed human caspase-1 in keratinocytes (Kcasp1Tg) investigated the effects of deleting IL-17A and IL-17F on visceral complications." (PMID 39519167, 2024). "In mannan-induced skin inflammation, an increased expression of the IL-17 family of cytokines (IL-17A, IL-17E, and IL-17F) was observed in the female mice." (PMID 35663991, 2022). "TPA led to localized skin inflammation with increased epidermal thickness, infiltration of inflammatory-like cells and augmented tissue interleukin-17F levels." (PMID 27401543, 2016). "However, the skin inflammation in AD is a mixture of many inflammatory cytokines, including IL-17A and IL-17F." (PMID 39519167, 2024). "In imiquimod-induced dermatitis, IL-17A, IL-17F, and IL-22 may be mostly derived from Th17 cells or γδT17 cells, while CXCL1, CXCL2, CCL20, and IL-17C may be mainly produced by epidermal keratinocytes." (PMID 37762500, 2023). "Oral propionate and the HFD reduced mRNA expression of IL-17A, IL-17C, IL-17F, IL-22, IL-1β, IL-6, TNF-α, CXCL1, CXCL2, and CCL20 in imiquimod-induced dermatitis." (PMID 37762500, 2023). "Oral propionate reduced inflammatory infiltrates and epidermal Ki67+ cells and reduced mRNA levels of IL-17A, IL-17F, IL-17C, IL-22, IL-1β, IL-6, TNF-α, CXCL1, CCL20 and increased those of TGF-β1and IL-10 in imiquimod-indued dermatitis." (PMID 37762500, 2023). "Oral propionate decreased mRNA expression of IL-17A, IL-17C, IL-17F, IL-22, IL-6, IL-1β, TNF-α, CXCL1, and CCL20 in imiquimod-induced dermatitis in comparison between NDIS versus NDIP." (PMID 37762500, 2023). "The HFD decreased mRNA expression of IL-17A, IL-17F, IL-22, TNF-α, IL-1β, CXCL1, CXCL2, and keratin 16, and increased mRNA expression of TGF-β1 and CDKN1A in imiquimod-induced dermatitis." (PMID 37762500, 2023). "HFD reduced mRNA levels of IL-17A, IL-17F, IL-22, IL-1β, tumor necrosis factor (TNF)-α, CXCL1, CXCL2, and keratin 16 and increased those of transforming growth factor (TGF)-β1 and cyclin-dependent kinase inhibitor 1A in imiquimod-induced dermatitis." (PMID 37762500, 2023). "All mice with oxazolone-induced dermatitis had a dramatic increase in IL-1β, IL-4, IL-6, IL-10, TNF-α, IFN-γ, IL-16, IL-17C, IL-17E, IL-17F, IL-21, IL-22, and MIP-3a, whereas the concentrations of IL-12p70, IL-2, IL-17A, and IL-23 were lower in dermatitis mice." (PMID 37889696, 2023). "Additionally, deletion of Brd4 in follicle stem cells also rendered them sensitive to cell death, which in turn triggered the activation of γδ T cells and production of potent inflammatory cytokines, including IL-17A, IL-17F, and IFN-γ, that subsequently mediate skin inflammation." (PMID 36256455, 2022).
Crohn disease (15 papers, 2010 to 2024). A gastrointestinal disorder characterized by chronic inflammation involving all layers of the intestinal wall, noncaseating granulomas affecting the intestinal wall and regional lymph nodes, and transmural fibrosis. "IL-17F rs763780 is also associated with an increased risk of the development of Crohn’s disease or ulcerative colitis development." (PMID 29874787, 2018). "Upregulated IL-17F expression was also reported in intestinal samples obtained from patients with active Crohn's disease." (PMID 33663574, 2021). "For patients with either Crohn’s disease or UC, Th17 cells are abundant in inflamed intestine terminal ileum and produce IL17A, IL17F, IL26 and IFNγ." (PMID 34390759, 2021).
breast cancer (14 papers, 2008 to 2024). A primary or metastatic malignant neoplasm involving the breast. "The increase in local mammary tumor recurrence in HFD offspring was linked to an increase in the markers of immunosuppression (Il17f, Tgfβ1, VEGFR2) in the tumor microenvironment (TME)." (PMID 32580156, 2020). "The expression levels of genes encoding downstream products of IL-17A/IL-17F signaling were downregulated in breast cancer with high ER expression." (PMID 33102239, 2020). "The consequence indicates that increased expression of IL-17A and IL-17F is associated with low levels of ER in breast cancer." (PMID 33102239, 2020). "Increased expression of PD-1/PD-L1 was associated with ER-negative status, IL-17A-positive status, IL-17F-positive status, and upregulation of IL-17 signaling pathway-related genes in breast cancer." (PMID 33102239, 2020). "On the other hand, the majority of genes encoding downstream products of IL-17A and IL-17F signaling transduction had increased expression levels in ER-negative and basal-like breast cancer." (PMID 33102239, 2020). "Genetic polymorphisms in IL-17F and IL-17A were reported to be significantly associated with susceptibility of breast cancer in human." (PMID 28101335, 2017). "Increased Th17 cells may accelerate the spread of breast cancer by secreting IL-17F, which causes breast cancer cells to activate the MAPK signaling pathway." (PMID 36386919, 2022). "Therefore, it is expected that genes related to the IL-17A/IL-17F signaling pathway increases immune infiltration in breast cancer tissues, especially genes that encode downstream products of IL-17A/IL-17F signaling transduction." (PMID 33102239, 2020). "Previous studies indicated that mutations in IL-17F and IL-17A genes were related with inflammatory conditions e.g. inflammatory bowel disease, asthma, rheumatoid arthritis, ovarian cancer, colon cancer and breast cancer." (PMID 28101335, 2017). "In our case-control study, for the first time we investigated the associations between eight SNPs in the IL-17A (rs2275913, rs3819025 and rs3748067) and IL-17F (rs763780, rs7771511, rs12203582, rs9382084 and rs1266828) genes and the risk of sporadic breast cancer in Chinese Han women." (PMID 22461912, 2012). "Both IL-17A and IL-17F gene polymorphisms may provide valuable information for predicting the prognosis and effectiveness of pharmaceutical treatment in Chinese breast cancer patients." (PMID 22461912, 2012). "From the analysis of clinical information in conjunction with IL-17A or IL-17F gene polymorphisms, we found that the IL-17A and IL-17F genes may influence the diagnosis, treatment, and prognosis of breast cancer." (PMID 22461912, 2012). "Both IL-17A and IL-17F gene polymorphisms may provide valuable information for predicting the prognosis of breast cancer in Chinese women." (PMID 22461912, 2012). "We found increased mRNA expression of Il17f, and a tendency toward an increase of Il17c and Il6, in the mammary tumors of HFD offspring." (PMID 32580156, 2020). "Furthermore, in the case of breast cancer, an HSD has been found to promote tumor progression and lung metastasis, increase the proportion of Th17 cells, and activate the MAPK/ERK signaling pathway in breast cancer cells through the secretion of IL-17F." (PMID 38462638, 2024). "Two studies have analysed IL-17F protein amount in breast cancer patients." (PMID 35012470, 2022). "In addition to those genes that encode downstream products of IL-17A/IL-17F signaling transduction, the expression levels of IFNG, FOS, FOSB1, and FOSL1 were also found to be associated with ER status in breast cancer." (PMID 33102239, 2020). "This suggests that ER downregulates the intensity of the response to IL-17A/IL-17F signaling in breast cancer, which might result from reduced IL-17A/IL-17F levels and decreased Th17 cell infiltration." (PMID 33102239, 2020).
breast cancer (continued). "However, compared with the control offspring, Il17f expression was significantly upregulated in mammary tumors of the offspring of HFD-fed dams obtained from TAM-treated tumors and recurring tumors (P = 0.04)." (PMID 32580156, 2020). "Since IL-17A, IL-17F, and IL-17C are initiators of IL-17 signal transduction, whereas IL-17E suppresses Th17 cell responses, ER downregulates IL-17 signal transduction in breast cancer by differentially regulating the expression of IL-17 cytokines." (PMID 33102239, 2020). "Although the significance of IL-17A and IL-17F in the pathogenesis of breast cancer is unclear, we hypothesized that both cytokines may affect the development of breast cancer, either coordinately or independently." (PMID 22461912, 2012). "We genotyped three single-nucleotide polymorphisms (SNPs) in IL-17A (rs2275913, rs3819025 and rs3748067) and five SNPs in IL-17F (rs7771511, rs9382084, rs12203582, rs1266828 and rs763780) to determine the haplotypes in 491 women with breast cancer and 502 healthy individuals." (PMID 22461912, 2012). "Furthermore, we are presently investigating the expression of the two key IL-17 receptor chains on breast cancer cells, RA and RC, which heterodimerise to mediate signalling following binding of IL-17A and IL-17F." (PMID 19014637, 2008). "It was also noticed in our study that transcripts encoding IL-17A and IL-17F in the majority of samples and transcripts encoding IL-17C and IL-17E in half of the samples were absent according to TCGA Breast Cancer dataset, which made the quantitative analysis difficult." (PMID 33102239, 2020). "In addition, it was demonstrated that rs2275913 in IL17A but not IL17F was associated with the risk of breast cancer." (PMID 23049595, 2012). "In mice with EO771 breast cancer, the abundances of CXCL1 in the diseased lungs of Ifng−/− mice and Il17a/Il17f−/− mice were 6% and 18% of that in the diseased lungs of mock C57 mice." (PMID 37553342, 2023). "Analysis of lung Vγ4+ and Vγ6+ cells in mammary tumor-conditioned lungs revealed that inhibition of ICOS, PD-1, or TIM-3 failed to alter the proportion of cells expressing IL-17A, IL-17F, TIM-3, or AREG." (PMID 36480166, 2023).